PRAMENP (PRAME N-terminal like, pseudogene )
Synonyms: PRAMEF24P; PRAMEL
Gene: Long non-coding RNA gene on chromosome 22 (21,991,099 to 22,043,934, reverse strand). Ensembl gene ENSG00000290847.
Diseases named in the same sentence as PRAMENP in open-access papers:
PRAMENP is named in the same sentence as 1 disease in open-access papers, as found by Europe PMC text mining. Sharing a sentence is not in itself a finding about the gene and the disease.
PRAMENP shares sentences with these, for which no sentence is quoted: chronic lymphocytic leukemia (1 paper).